RN7SL321P (RNA, 7SL, cytoplasmic 321, pseudogene)
Gene: Miscellaneous RNA gene on chromosome 3 (48,379,834 to 48,380,132, forward strand). Ensembl gene ENSG00000277483.
Homologues: Orthologues: chimpanzee Metazoa_SRP (99% identical), macaque Metazoa_SRP (93% identical). Paralogues in human: RN7SL1 (84% identical), RN7SL2 (84% identical), RN7SL3 (84% identical), RN7SL589P (81% identical), RN7SL650P (81% identical), RN7SL228P (81% identical), RN7SL296P (81% identical), RN7SL413P (81% identical), RN7SL47P (81% identical), RN7SL575P (81% identical), RN7SL678P (81% identical), RN7SL709P (81% identical), and 702 more.